HAVCR2 (hepatitis A virus cellular receptor 2)
Diseases named in the same sentence as HAVCR2 in open-access papers (continued):
Sharing a sentence is not in itself a finding about the gene and the disease.
tumor (continued). "TIM-3, also known as hepatitis A virus cell receptor 2 (HAVCR2) or CD366, is another promising inhibitory receptor among numerous emerging immune checkpoints and has achieved initial anti-tumor effects in clinical trials of its monotherapy or combination with anti PD-1/PD-L1 drugs." (PMID 38177102, 2024). "Several immune checkpoint genes (HAVCR2, CD47, LGALS9, and CD276) were gradually upregulated along the DC differentiation trajectory, especially at the late stage, revealing that C3-DC might suppress tumor immunity." (PMID 36788228, 2023). "Importantly, the tumor immune dysfunction and exclusion (TIDE) algorithm showed that in CCL2-high GBM group, the expression of CD274, CTLA4, HAVCR2 and other immune checkpoints were significantly increased, and the immune checkpoint blockade (ICB) therapy was accordingly more responsive." (PMID 38057698, 2023). "Furthermore, KIF18A expression was positively correlated with many common immune checkpoints, including PD-L1, PD-1, CTLA4, TIGIT, HAVCR2, PDCD1LG2, and LAG3, indicating that KIF18A may be a new target for tumor immunotherapy." (PMID 36830695, 2023). "CD8 Tex with elevated expression of multiple inhibitory receptors (PDCD1, CTLA4, LAG3, TIGIT, HAVCR2) and Tregs with high expression levels of FOXP3, TIGIT, and CTLA4 were enriched in the ESCC TME, which contributed to tumor immune escape and immunotherapy resistance." (PMID 37187751, 2023). "Notably, we detected that the HAVCR2 expression is related to the G protein-coupled receptor (GPCR) ligand binding pathway and interleukin pathway generally, which may regulate tumor metabolism and the microenvironment." (PMID 36081997, 2022). "Therefore, we further compared the expression of immune checkpoint genes in tumor tissues of the high SIRGs score group and the low SIRGs score group and found that PD-L1, CTLA-4, HAVCR2, LAG3, TIGIT and PDCD1 were also up-regulated in the high SIRGs score group." (PMID 36052090, 2022). "There is evidence that T cells lose their effector function and ability to kill tumor cells when stimulated by tumor antigens, which may be due to the increasing diversity and number of inhibitory receptors, including CD274, PDCD1LG2, HAVCR2, CTLA4, LAG3, PDCD1, TIGIT." (PMID 33592580, 2021). "TIM-3, also known as HAVCR2 could be an interesting and promising target for anticancer immunotherapy, since it is expressed on a variety of T-cells, DCs (dendritic cells), macrophages and monocytes and elicits a strong innate anti-tumor immune response." (PMID 31960110, 2020). "This suggests that activated CD8+ T cells in cluster L0, which express the immune inhibitory checkpoint molecules Tim3 (Havcr2) and Lag3, and which are enriched in transplant but not primary tumors, may mediate transplant tumor cure by anti-PD-1 therapy." (PMID 33335088, 2020). "Compared to normal samples, although MAIT cells reduced in HCC, tumor-derived MAIT cells down-regulated genes enriched in the cytokine secretion and cytolytic effect pathways (NFKB1 and STAT5B) and up-regulated genes such as IL8, CXCL12 and HAVCR2 (TIM -3) promote tumor development." (PMID 33574818, 2020). "TIM-3 (T cell immunoglobulin and mucin-domain containing-3, also known as HAVCR2) is a member of the T-cell immunoglobulin- and mucin-domain-containing family that plays an important role in promoting T-cell exhaustion in both chronic viral infections and tumor escape from immune surveillance." (PMID 30863404, 2019). "Moreover, a high THEMIS2 expression was associated with increased levels of immune checkpoint molecules, such as PD-1, PD-L1, CTLA-4, and HAVCR2, indicating that THEMIS2 might contribute to establishing an immunosuppressive TME that facilitates tumor immune escape." (PMID 39851494, 2025).
tumor (continued). "We investigated the expression of HAVCR2 and LGALS9, typical immune suppressive genes, and CD163, an M2 macrophage marker gene, and found that they were co-expressed in the macrophage clusters, indicating that the TAMs infiltrating the tumor might be M2 subtype." (PMID 39474422, 2024). "Indeed, CD8+ T cells in the tumor periphery showed increased expression of genes belonging to costimulatory pathways, including ICOS, TNFRSF4 (OX40) and TNFRSF9 (4-1BB), albeit accompanied by high levels of inhibitory receptors PDCD1 (PD-1), LAG3, HAVCR2 (TIM-3), and CTLA4." (PMID 38127790, 2023). "PD-1, CTLA4, LAG3, TIGIT, and TIM-3 (HAVCR2) are known as inhibitory molecules expressed in exhausted T cells that have an impaired ability to kill tumors because they neither respond to T cell receptor stimulation nor secrete anti-tumor cytokines such as interferon γ and tumor necrosis factor-α." (PMID 35480109, 2022). "Across tumor types, this analysis identified signaling to CD8+ T cells via HAVCR2-LGALS9 (TIM3-Galectin9) as enhanced in non-responding and resistant patients." (PMID 35572582, 2022). "HAVCR2 (TIM-3), highly expressed on innate cells, acts as a negative regulator of Th1 and CTL responses and critically involves in tumor growth." (PMID 34249910, 2021). "With our model we were able to obtain good fits if the exhausted state was correlated with HAVCR2 or LAG3 but not with PDCD1/CD274, which was due to the early peak of Pdcd1 and Cd274 transcription that was already well in decline on day 5 while CTL numbers in the tumor remained high." (PMID 37182110, 2023).
cancer (924 papers, 2012 to 2026). A tumor composed of atypical neoplastic, often pleomorphic cells that invade other tissues. "According to a recent study, mRNA and protein levels of hepatitis A virus cellular receptor 2 gene (HAVCR2) encoding the potential immune-checkpoint target T-cell immunoglobulin mucin 3 protein are highly upregulated in multiple cancer types, including OSC." (PMID 38970121, 2024). "This study comprehensively analyzed HAVCR2 expression patterns in pan-cancer and underlined its potential value for immune checkpoint inhibitor-based immunotherapy." (PMID 36081997, 2022). "These observed associations existed between HAVCR2 and recognized immune checkpoints in most cancers, suggesting a potential synergy treatment effect." (PMID 36081997, 2022). "In conclusion, differential HAVCR2 expression was significantly associated with prognosis, immune cell infiltration, and immune-related markers in pan-cancer." (PMID 36081997, 2022). "The heatmap represented HAVCR2 expression that was substantially linked with different immune infiltrating cells and their subtypes in pan-cancer." (PMID 36081997, 2022). "Enrichment analyses implicated HAVCR2-associated terms in cancer, including immunity, metabolism, and inflammation." (PMID 36081997, 2022). "The -1516G>T, -574G>T, and +4259T>G of the HAVCR2 gene are the most studied polymorphisms in terms of association with overall cancer risks." (PMID 33519815, 2020). "T cell immunoglobulin and mucin domain-containing protein-3 (Tim-3) is an immunoregulatory protein encoded by the Hepatitis A virus cellular receptor 2 (Havcr2) gene and is an emerging target for cancer immunotherapy." (PMID 32932843, 2020). "The authors concluded that their study clearly demonstrated involvement of HAVCR2 gene polymorphisms (minor alleles of examined SNPs) in conferring higher risk for development of different human cancers." (PMID 33519815, 2020). "Deeper understanding of how 3′UTR variants influence activity by TIM-3/HAVCR2 is useful for research into cancer therapy." (PMID 29796301, 2018). "Deeper understanding of how 3′UTR variants influence the activity by TIM-3/HAVCR2 for therapy against cancer." (PMID 29796301, 2018). "Similarly, a promising area of investigation in SETD2-mutated cancer is into immune checkpoint expression, such as HAVCR2, CTLA-4, or TIGIT or biomarkers such as CDCP1 and AXL." (PMID 41228333, 2025). "We also analyzed the mutation patterns of the HAVCR2 gene in diverse cancers additionally." (PMID 36081997, 2022). "A key finding in our study was that HAVCR2 expression was associated with cancer immunity." (PMID 36081997, 2022). "However, the profile of the hepatitis A virus cellular receptor 2 (HAVCR2) gene, encoding TIM-3 expression, is still obscure, along with its role in cancer immunity and prognosis." (PMID 36081997, 2022). "Among this family, TIM-3, encoded by the HAVCR2 gene and its ligands, is presently attracting increasing attention because of its potential as a target for immunotherapy of different diseases, such as cancers." (PMID 33425759, 2020). "Various groups have analyzed the link between TIM-3/HAVCR2 polymorphisms and the risk of cancer." (PMID 29796301, 2018). "TIM-3, encoded by the hepatitis A virus cellular receptor 2 gene (HAVCR2), is a trans-membrane receptor expressed by a wide range of cells including T lymphocytes, innate immune cells such as monocytes, natural killer (NK), and dendritic cells (DC), and additionally on cancer stem cells." (PMID 31747929, 2019). "We examined the relationship between EIF5A2 and immune checkpoints using Spearman analysis and found that EIF5A2 was correlated with CD274, PDCD1LG2, and HAVCR2 in the majority of cancers and PDCD1, CTLA4, LAG3, SIGLEC15, and TIGIT in some tumors." (PMID 40964657, 2025). "Elevated levels of HAVCR2 expression facilitate the development of tumors, the rapid growth of cancer cells, and their ability to invade surrounding tissues by inhibiting the actions of immune cells." (PMID 39670859, 2025).
cancer (continued). "The relationship between the expression level of HAVCR2 and cancer immune infiltration, as well as immune checkpoint genes, has been well-documented." (PMID 40076932, 2025). "Consistent with murine studies, well-known Tex genes (CTLA4, LAG3, HAVCR2 (gene encoding Tim-3), PDCD1, TIGIT, TOX) were among the most prominently represented in Tex from human cancers." (PMID 40236693, 2025). "TIM-3, also known as hepatitis A virus cellular receptor 2 (HAVCR2), is an immune inhibitory surface molecule expressed on various immune cells, including T cells, Treg cells, DCs, NK cells, macrophages, and cancer cells." (PMID 39915447, 2025). "Elevated HAVCR2 expression is a recurring phenomenon in cancer cells, it holds predictive power for aggressive disease progression and poor prognosis." (PMID 38568056, 2024). "We investigated the methylation levels (beta values) of TIGIT, CXCL13, LAYN, LAG3, PDCD1, and HAVCR2 across different cancer types." (PMID 39064019, 2024). "The exhaustion of CD8 + T and NK cells, along with the overexpression of molecular markers such as LAG3, CTLA4, CD274, PD-L1, and HAVCR2, have been identified as key mechanisms by which cancer cells can escape host immunity." (PMID 38956740, 2024). "Analyzing our data, we show that HAVCR2 expression is increased in the majority of the different cancer types." (PMID 39064019, 2024). "We next examined the associations of TLR4 expression with 8 immune checkpoints (PD-L1, CTLA4, HAVCR2, LAG3, PDCD1, PDCD1LG2, SIGLEC15, and TIGIT), and TLR4 expression was widely associated with the 8 immune checkpoints in most cancer types." (PMID 37576399, 2023). "Recent studies have shown that HAVCR2, a modular receptor with multiple co-inhibitory receptors (e.g., checkpoint receptors), is present on exhausted T cells in various cancers." (PMID 37744335, 2023). "Specifically, several immune checkpoints including TNFRSF18, TNFRSF4, VSIR, LGALS9, HAVCR2, and TNFRSF14 are significantly associated with RARA-AS1 in more than 10 types of cancer." (PMID 37833349, 2023). "PD-1, CTLA4, LAG3, and HAVCR2 are T cell depletion markers, and the T cell depletion is a major factor contributing to immune dysfunction in cancer patients." (PMID 36785788, 2023). "HAVCR2/TIM-3 has been reported to be upregulated in response to PD-1 blockade in various cancer models, and overexpression of HAVCR2/TIM-3 and VISTA has been associated with lack of response to anti-PD-1/PD-L1–based therapies." (PMID 36968142, 2023). "The present study comprehensively analyzed the expression, prognosis, functions, and pathways of HAVCR2 in pan-cancer and unveiled its potential application in immune treatment." (PMID 36081997, 2022). "The present study first demonstrated a comprehensive landscape for HAVCR2 systematically and extensively to explore its instrumental role in pan-cancer." (PMID 36081997, 2022). "For the analysis of 24 immune-inhibiting genes, we found that SERPINH1 expression was highly associated with CD276, TGFBI, VEGFA, HAVCR2, IL10, and ADORA2A in most cancers." (PMID 36105106, 2022). "TIM3 (HAVCR2) (Hepatitis A Virus Cellular Receptor 2) is a key checkpoint molecule inhibiting the innate and adaptive immune response in cancer." (PMID 36224560, 2022). "We found that the HAVCR2 gene was strikingly linked to MSI in KIRC (p = 0.0045), LGG (p = 0.0073), and SKCM (p = 0.00027) in eight prognosis-related cancers." (PMID 36081997, 2022). "Our study first provided broad insight into differential expressions and related mechanisms of HAVCR2 in the pan-cancer dataset." (PMID 36081997, 2022). "Our results displayed that HAVCR2 was differentially expressed and closely corresponded to survival status in pan-cancer." (PMID 36081997, 2022). "More importantly, the HAVCR2 expression level was also significantly related to cancer immune infiltration, immune checkpoint genes, and immune marker genes." (PMID 36081997, 2022).
cancer (continued). "We further determined the effect of aberrant HAVCR2 expression on prognosis by using Kaplan–Meier plotter in pan-cancer." (PMID 36081997, 2022). "Our results displayed that HAVCR2 had multifaceted prognostic values of disease-specific survival, overall survival, and progress-free survival in different types of cancer." (PMID 36081997, 2022). "Our findings brought to light that PTX3 had a close and positive association with most ICIs (CD274, CTLA4, HAVCR2, LAG3, PDCD1, PDCD1LG2, TIGIT, and SIGLEC15) in TCGA cancers, except TGCT." (PMID 36139597, 2022). "HAVCR2, also known as TIM-3 (T-cell immunoglobulin domain and mucin domain-3), is involved in the pathogenesis of malignant tumors and the progression of various types of cancer." (PMID 35774505, 2022). "Altogether, these results suggest that HAVCR2 expression was a key driver of immune response and cancer." (PMID 36081997, 2022). "Immune checkpoint inhibitors (ICIs) related biomarkers discovered that high-risk group was positively correlated with high expression of HAVCR2 in digestive system pan-cancer." (PMID 35574385, 2022). "The expression of immune checkpoint (ICP) genes, such as PDCD1 (PD1), CD274 (PDL1), CTLA4, LAG3, and HAVCR2 (TIM3) has been utilized in predicting the response of patients to immune checkpoints therapy in a variety of cancers including PAAD." (PMID 35601487, 2022). "Based on these results, our findings revealed that cancer immunity is positively correlated with the HAVCR2 expression." (PMID 36081997, 2022). "Methylation of CpGs annotated to the promoters of LAG3, CTLA4, CD86, CD80, and HAVCR2 also decreases with age pan-cancer." (PMID 34433020, 2021). "The expression of immune checkpoint genes [e.g., PDCD1 (PD1), CD274 (PDL1), CTLA4, LAG3, and HAVCR2 (TIM3)] has been utilized in predicting the response of patients to ICB therapy in a variety of cancers including CC." (PMID 34733790, 2021). "The results suggested that UBE2C expression was positively associated with the immune checkpoint-related genes in 31 cancers, which mainly included CD274, CTLA4, HAVCR2, LAG3, PDCD1, PDCD1LG2, SIGLEC15, and TIGIT." (PMID 34858987, 2021). "Frequency of genetic variants of CTLA-4, PDCD1, PD-L1, BTLA, HAVCR2, and LAG3 genes (in different human populations) for which the association with cancer risk has been investigated." (PMID 33519815, 2020). "TIM-3/HAVCR2 is involved in the pathogenesis of malignant tumors and progression of various types of cancer." (PMID 29796301, 2018). "TIM-3, also known as HAVCR2, is another immune checkpoint receptor that is currently being tested in preclinical models for its potential to re-invigorate exhausted T cells in cancer patients." (PMID 27148271, 2016). "However, we discovered that CD48, CD86, and HAVCR2 were common factors in both cohorts, indicating a potential synergistic effect by targeting both ferroptosis pathways and immune checkpoints in cancer therapy." (PMID 40744688, 2025). "Interestingly, HAVCR2 was one of the most transcriptionally enriched genes in myeloid cells from ICI-unresponsive patients in their cross-cancer dataset." (PMID 39953623, 2025). "Additionally, it was illustrated that ANKRD27 expression showed a positive correlation with the level of inhibitory immune checkpoints, such as CD274, PDCD1, CTLA4, and HAVCR2, across various types of cancer." (PMID 39834932, 2024). "Notably, CDR C0 group was infiltrated with co-inhibitors and had higher expression of HAVCR2 than C2, C3, C4, providing sites for ICIs to combine and increasing anti-cancer CD8+ T cells immunity." (PMID 38977778, 2024). "To this end, we explored the mutation rate of the Tex signature genes in pan-cancer, and we observed a 2–3% SNV mutation frequency of PDCD1, LAG3, TIGIT, HAVCR2, and LAYN mainly in UCEC and SKCM, with HAVCR2 and TIGIT having the highest mutation frequencies (24% and 23% of samples, respectively)." (PMID 39064019, 2024).